GEN1 (GEN1 structure-specific endonuclease)
Description:
Endonuclease which resolves Holliday junctions (HJs) by the introduction of symmetrically related cuts across the junction point, to produce nicked duplex products in which the nicks can be readily ligated. Four-way DNA intermediates, also known as Holliday junctions, are formed during homologous recombination and DNA repair, and their resolution is necessary for proper chromosome segregation. Cleaves HJs by a nick and counter-nick mechanism involving dual coordinated incisions that lead to the formation of ligatable nicked duplex products. Cleavage of the first strand is rate limiting, while second strand cleavage is rapid. Largely monomeric, dimerizes on the HJ and the first nick occurs upon dimerization at the junction. Efficiently cleaves both single and double HJs contained within large recombination intermediates. Exhibits a weak sequence preference for incision between two G residues that reside in a T-rich region of DNA. Also has endonuclease activity on 5'-flap and replication fork (RF) DNA substrates.
Synonyms: FLJ40869; Gen
Tractability: PROTAC: ubiquitination databases record sites on it.
Gene: Protein-coding gene on chromosome 2 (17,753,278 to 17,788,946, forward strand). Ensembl gene ENSG00000178295.
Subcellular location: Nucleus
Subcellular location (Human Protein Atlas): Nucleoplasm
Pathways (Reactome):
DNA Repair: Resolution of D-loop Structures through Holliday Junction Intermediates
Gene Ontology:
Molecular function: 5'-flap endonuclease activity; crossover junction DNA endonuclease activity; four-way junction DNA binding; magnesium ion binding; protein homodimerization activity; catalytic activity; DNA binding; nuclease activity
Biological process: double-strand break repair via homologous recombination; positive regulation of mitotic cell cycle spindle assembly checkpoint; regulation of centrosome duplication; replication fork processing; resolution of DNA recombination intermediates; resolution of mitotic recombination intermediates; DNA recombination
Cellular component: centrosome; nucleoplasm; nucleus
Genetic constraint (gnomAD): Loss-of-function variants: 20 observed, 20.43 expected, observed/expected ratio (o/e) 0.98, 90% interval 0.69 to 1.42. The upper end of that interval is the gene's LOEUF score, 1.42, which puts it in group 5 of 6, group 1 being the genes least tolerant of losing a copy. Missense variants: 719 observed, 721.7 expected, observed/expected ratio (o/e) 1, 90% interval 0.94 to 1.06. Synonymous variants: 258 observed, 253.93 expected, observed/expected ratio (o/e) 1.02, 90% interval 0.92 to 1.13.
Gene-disease validity (ClinGen):
ClinGen rates the evidence that GEN1 causes each of these diseases.
hereditary breast carcinoma (autosomal dominant): Refuted. Breast carcinoma that has developed in relatives of patients with history of breast carcinoma.
familial ovarian cancer (autosomal dominant): No Known Disease Relationship. An instance of ovarian cancer that is caused by an inherited modification of the individual's genome.
Homologues: Orthologues: chimpanzee GEN1 (99% identical), macaque GEN1 (93% identical), dog GEN1 (79% identical), pig GEN1 (77% identical), rabbit GEN1 (77% identical), rat Gen1 (70% identical), mouse Gen1 (70% identical), guinea pig GEN1 (68% identical), tropical clawed frog gen1 (46% identical), Drosophila melanogaster Gen (23% identical). Paralogues in human: EXO1 (14% identical), FEN1 (10% identical).